VIM (vimentin)
Diseases named in the same sentence as VIM in open-access papers (continued):
Sharing a sentence is not in itself a finding about the gene and the disease.
lung carcinoma (continued). "Whereas, lung cancer A549 and SK-MES-1 cells expressed high level of E-cadherin, and low level of α-SMA and vimentin." (PMID 29100297, 2017). "The existence of EMT was tested in lung cancer cells by the three color immune-fluorescent staining (CK, CD45 and Vimentin) with the size-based microfluidic chip." (PMID 28039472, 2017). "Recent studies have demonstrated that several markers of cancer stem cells in lung cancer, such as CD44, CD133 and ALDH1, are closely correlated with vimentin expression and the EMT in lung cancer." (PMID 27657690, 2016). "In consistent with such studies, our results showed that zinc-treated lung cancer cells displayed the elongated mesenchymal-like shape with the significant increase of EMT markers namely N-cadherin, vimentin, snail and slug." (PMID 27330411, 2016). "Through the regulation of ZEB (zinc finger E-box-binding homeobox) transcription factors (ZEB1 and ZEB2), E-cadherin (CDH1), vimentin (VIM), the down-regulated miR-200 family promotes EMT in the progression of lung cancer." (PMID 27005669, 2016). "All the lung cancer samples (including CIS, A and AM, totally 66 samples) expressed different levels of α-SMA, vimentin, E-cadherin, Twist and TGF-β." (PMID 25189096, 2014). "We used immunofluorescence and QRT-PCR to examine the expression and distribution of E-cadherin, pancytokeratins, vimentin, α-smooth muscle actin (α-SMA) and fibronectin in heterotypic hybrids and in their respective parental lung cancer cells." (PMID 24516569, 2014). "Noncytotoxic doses of NO enhanced anoikis resistance and migration in lung cancer H23 cells via an increase in lamellipodia, epithelial-mesenchymal transition (EMT) markers including vimentin and snail, and caveolin-1 (Cav-1)." (PMID 24967418, 2014). "Immunoblotting analysis revealed that treatment with rVP1 (0.4 μM) for 24 h attenuated EMT by upregulating E-cadherin and downregulating vimentin expression levels in A549, H1299 and CL1-5 lung cancer cell lines." (PMID 25004182, 2014). "This has been recently shown in a series of patients with resectable lung cancer, where a significant proportion of CTC identified by ISET either co-expressed cytokeratins and vimentin or expressed vimentin alone." (PMID 21829190, 2011). "In lung carcinoma, IL27 down-regulates vimentin expression and reduces cellular migration and invasion." (PMID 21559505, 2011). "In the lung cancer cell line H1299, TET1 is required for the expression of mesenchymal genes N-cadherin and vimentin as well as for the expression of INSIG1, a master regulator of cholesterol biosynthesis that drives hypoxia-induced EMT in a catalytic-site independent manner." (PMID 40764968, 2025). "Also, LDHA knockdown in lung cancer cells resulted in MET induction through decreased E-cadherin and increased vimentin, N-cadherin, Snail, and ZEB1 expression." (PMID 40507273, 2025). "Therefore, we isolated CAFs from lung cancer tissues using enzymatic digestion, and immunofluorescence analysis confirmed the positive expression of CAF markers Vimentin, FSP1, and alpha-SMA." (PMID 39010054, 2024). "Our results showed that, in 34 cases of lung cancer, the CDH1 demonstrated lower expression, while N-cadherin and vimentin had higher levels of expression in tumor tissues, which were significantly different from those in the corresponding noncancerous tissues (n = 34)." (PMID 36711024, 2023). "Indeed, a significant positive correlation between low E-cadherin/high vimentin expression (an important EMT feature) and worse overall survival of lung cancer patients has been reported." (PMID 38139154, 2023). "Note that while ZO-1 and ZO-2 efficiently suppressed the metastatic potential of lung cancer cells, there was no significant impact on the expression of EMT-associated proteins, such as E-cadherin, N-cadherin, and vimentin." (PMID 37240145, 2023).
lung carcinoma (continued). "Moreover, we found that herboxidiene can completely inhibit the basal expression of the epithelial marker E-cadherin, the TGF-β-induced expression of mesenchymal markers, including N-cadherin, vimentin and SNAIL, and the migration of lung cancer A549 cells." (PMID 36646950, 2023). "In addition, immunoblotting demonstrated that EGFR signaling and EMT related proteins (Vimentin and SNAIL) were considerably downregulated after PELI1 knockdown in these two lung cancer cell lines." (PMID 36841821, 2023). "EMT marker Twist knockdown induces caspase-3- and -7-dependent apoptotic cell death by inhibiting the phosphorylation of EGFR, Akt, vimentin, and Twist1, and by activating E-cadherin in EGFR-TKI gefitinib and AZD9291-treated gefitinib-resistant lung cancer cells." (PMID 36768961, 2023). "Indeed, the ubiquitination of Vimentin influenced by symmetric dimethylarginine (sDMA) is thought to be necessary for the roles of MTAP and PRMT5 in lung cancer metastasis." (PMID 36969045, 2023). "In addition, overexpression of SCARA3 reduced migration and invasion ability of lung cancer cells and induced decreases of EMT markers such as β-catenin, vimentin, and MMP9." (PMID 35578316, 2022). "Similarly, in experiments involving lung cancer cells have shown that the knockdown of RKIP produced the production of EMT proteins such as vimentin, once again showing that vimentin exists downstream of the effect of RKIP." (PMID 36230521, 2022). "MTHFD2 was involved in lung cancer cell proliferation, migration, and apoptosis by mediating its downstream molecules, such as DNA helicases (MCM4 and MCM7), as well as ZEB1, Vimentin and SNAI1, which contributed to tumor cell growth and epithelial-to-mesenchymal transition (EMT) process." (PMID 35790743, 2022). "Interestingly, CBD blocked epithelial growth factor mediated lung cancer cell migration in vitro controlling the levels of EMT genes, such as vimentin, supporting our observations." (PMID 36297277, 2022). "In addition, ectopic FOXA1 expression significantly reversed TGFβ1-mediated expression of EMT markers, such as CDH1, CDH2, VIM, SNAI2, and PTHLH, in A549 lung cancer cells." (PMID 35897813, 2022). "Indeed, we found that loss of FOXA1 and PGC1α decreased E-cadherin and increased N-cadherin and vimentin expression, which was significantly reversed by ectopic ID1 expression in A549 lung cancer cells." (PMID 35897813, 2022). "In previous studies, ID1 was shown to participate in liver metastasis of lung cancer cells through EMT and knockout of ID1 may lead to decreased expression of vimentin, TGF-β and Snail." (PMID 33992097, 2021). "In addition to apoptosis induction, ephemeranthol A inhibits the migration of lung cancer cells by inactivating AKT and subsequently suppressing the expression of EMT markers such as N-cadherin, vimentin and slug." (PMID 34279440, 2021). "PI3K and MEK inhibitors may block OPN‐increased intermediate filaments of cell type‐specific fiber networks by downregulating gene expression of vimentin, leading to the poor plasticity and EMT formation of lung cancer cells." (PMID 34323425, 2021). "Besides, miR-182-5p upregulated the expression of Twist, MMP-2 (matrix metallopeptidase 2), MMP-9 (matrix metallopeptidase 9), N-cadherin, Vimentin, and Snail proteins, which promoted the EMT process in lung cancer." (PMID 34729113, 2021). "The mesenchymal markers Matrix metalloproteinase-2 (MMP2), Vimentin, N-cadherin, Snail and Slug were significantly down-regulated, whereas the epithelial markers E-cadherin was notably upregulated by FOXH1 depletion in both lung cancer cell lines." (PMID 34090445, 2021). "Also, TCM decoction was found to markedly inhibit the EMT of lung cancer cells by downregulating the activator of STAT3 and mesenchymal markers such as N-cadherin and vimentin." (PMID 34867344, 2021).
lung carcinoma (continued). "Our results suggesting physical binding to circPTK2 to vimentin, which is distinguished from circPTK2 (hsa_circ_0008305), acting as a sponge for miR-429 / miR-200b-3p in non-small cell lung cancer cells and hereby inhibiting EMT in lung cancer cells." (PMID 31973707, 2020). "Additionally, Western blot indicated that miR-374a and miR-374b enhanced ZEB1 and vimentin protein levels, indicating that miR-374a and miR-374b partially induced EMT in lung cancer cells." (PMID 32674274, 2020). "Similarly, fusion between lung cancer cells and MSCs leads to enhanced metastasis through EMT, with downregulation of E-cadherin and upregulation of N-cadherin, vimentin, α-SMA, and fibronectin-1." (PMID 32632040, 2020). "Moreover, through Western blot analysis of lung cancer cells treated with lung CSC‐derived exosomes, we demonstrated that expression levels of N‐cadherin, vimentin, MMP‐9 and MMP‐1 were up‐regulated, whereas E‐cadherin expression was down‐regulated." (PMID 32396269, 2020). "By contrast, silencing VAL in cultured primary lung cancer cells (LAD3) originated from a stage III LAD patient’s primary lung tumor, in which VAL was also highly expressed and able to bind Vimentin protein, significantly suppressed the protein level rather than the mRNA level of Vimentin." (PMID 33046716, 2020). "In lung cancer, miR‐598, as a tumour suppressor, reported to negatively regulate EMT thereby suppressing the invasion and migration in NSCLC cells through increasing E‐cadherin and decreasing vimentin expressions." (PMID 32248643, 2020). "Interestingly, HAI-2 overexpression restored the expression of E-cadherin and down-regulated N-cadherin and Vimentin, suggesting that HAI-2 can promote the mesenchymal epithelial transition (MET) of lung cancer cells." (PMID 30765871, 2019). "An important role of calcium as an intracellular messenger within this process has ever been proposed by others since inhibition of specific calcium channels or calcium chelation in lung cancer cells limits TGF-β-induced EMT though the limitation of N-cadherin and vimentin expression." (PMID 30875855, 2019). "The lung cancer cell line A549 exhibited a decreased expression of the epithelial marker CK18 when cultured in MEM and DMEM but a more pronounced expression of the mesenchymal marker Vimentin." (PMID 31091728, 2019). "Furthermore, aberrant expression of BCL2L1 significantly altered the expression of lung cancer biomarkers such as MYC, EGFR, and Vimentin." (PMID 31508368, 2019). "Indeed, there was a significant correlation between levels of AXIN2 and the EMT markers VIM (Vimentin) and ZEB1 (Zinc Finger E-Box Binding Homeobox 1), which again was lost in tumor samples from Metformin-taking lung cancer patients." (PMID 29977599, 2018). "Cell line studies in human pancreatic ductal adenocarcinoma, endometrial, breast and lung cancer cells showed that treatment with TGF-β1 initiated transcription factor slug, not only resulting in upregulated L1CAM/vimentin and downregulated E-cadherin, but also in enhanced cell invasion." (PMID 29152102, 2017). "Concomitantly, the levels of Vimentin and N-cadherin were considerably down-regulated in siSPC24 cells, suggesting a promoting role of SPC24 in the regulation of epithelial-mesenchymal transition (EMT) for lung cancer." (PMID 29029446, 2017). "In addition, the IF protein vimentin, VAV2, and Rac1 interact in the regulation of the invasive capacity of lung cancer cells by controlling the formation of focal adhesions via FAK." (PMID 29152145, 2017). "In addition, IL-27 directly suppresses tumorigenicity through downregulation of vimentin, COX-2, and PGE2 on lung cancer cells." (PMID 25969628, 2015). "In lung cancer cells, phosphorylated Rac1 GEF VAV2 colocalizes with FAK at focal adhesion sites and activates Rac1 signaling, allows FAK phosphorylation, and promotes cell attachment in vimentin-expressing cells." (PMID 25965826, 2015).
lung carcinoma (continued). "The knockdown or knockout of RSK2 in A549 lung cancer cells or MEFs revealed that magnolin targeting ERKs/RSK2 signaling suppressed epithelial-to-mesenchymal transition by modulating EMT marker proteins such as N-cadherin, E-cadherin, Snail, Vimentin and MMPs." (PMID 26253302, 2015). "In contrast, we found that fucoidan enhances the expression of E-cadherin but reduces the expression of N-cadherin and Vimentin at 24 and 48 h in CL1-5 cells in a dose-dependent manner (data not shown), suggesting that fucoidan inhibits cell mobility and alters the EMT in lung cancer cells." (PMID 25149540, 2014). "Moreover, gefitinib-resistant lung cancer cells have EMT phenotype with down-regulation of E-cadherin and up-regulation of Vimentin." (PMID 24158561, 2013). "We first detected the expressions of Kindlin-1 and Kindlin-2 as well as epithelial to mesenchymal transition (EMT) markers E-cadherin and Vimentin in lung cancer cell lines derived from SCC, AC and LCC and found that Kindlin-1 and Kindlin-2 were differentially expressed in lung cancer cell lines." (PMID 23209705, 2012). "Furthermore, overexpression of miR-23a decreased E-cadherin expression and increased levels of vimentin, resulting in the EMT phenomenon in A549 lung cancer cells; silencing of miR-23a partially restored E-cadherin expression." (PMID 22752005, 2012). "The absence of E-cadherin expression and the presence of vimentin expression suggest that this ALK-rearranged lung cancer may have undergone epithelial-mesenchymal transition, resulting in the loss of cellular adhesiveness." (PMID 37920641, 2023). "In addition, a small molecule drug known as moscatilin has been shown to reverse EMT in lung cancer cells without inducing cytotoxic effects by suppressing mesenchymal markers such as vimentin, Snail and Slug." (PMID 35804837, 2022). "However, it is worth noting that the expression of vimentin, the EMT marker, in lung cancer tissues tends to increase (P=0.07), while HIIE tends to increase the expression of vimentin (P=0.07), which indicates that HIIE tends to enhance EMT in lung cancer cells." (PMID 35371324, 2022). "In the present study, it was found that N-cadherin, Vimentin, and Snail expression was upregulated in both A549 and PC9 cells following CoCl2-induced hypoxia, whereas expression of E-cadherin was downregulated, indicating EMT procedure activation in lung cancer cells." (PMID 35745677, 2022). "In this study, we irradiated cervical cancer HeLa cells and lung cancer A549 cells and found that 4 Gy 60Co γ-irradiation induced EMT, characterized by decreased expression of the epithelial marker E-cadherin and enhanced expression of the mesenchymal markers N-cadherin and vimentin." (PMID 36199069, 2022). "Willumsen and colleagues showed that MMP-degraded collagen 1 (C1M) and MMP-degraded citrullinated vimentin (VICM) are significantly elevated in serum from lung cancer patients compared with healthy donors, with excellent performance in detecting subjects with lung cancer." (PMID 30678058, 2019). "Immunofluorescence assays of Vimentin and Snail, the representative EMT markers, were consistent with these results, indicating that TESC may also be partially involved in the regulation of EMT initiation and progression in lung cancer." (PMID 30013043, 2018). "Therefore, to further evaluate whether miR-200c can inhibit EMT processes in lung cancer, we examined the expression of α-SMA, vimentin, and β-catenin expression by real-time PCR, western blotting, and immunocytochemical staining." (PMID 28727734, 2017). "All examined lung cancer cell lines tested GFP+/CD45− using TelomeScan F35 and could further be identified by immunohistochemical staining of epithelial (cytokeratin, E-cadherin, or EpCAM), mesenchymal (vimentin), or cancer stem cell (CD133) markers." (PMID 28432274, 2017).
lung carcinoma (continued). "In addition, knockdown of Nm23-H1 also altered the polymerization of actin and increased the protein levels of EMT-related proteins, fibronectin, N-cadherin, vimentin, phospho-FAK and vinculin, implying that a decrease in Nm23-H1 increases the invasive ability of lung cancer cells." (PMID 28831131, 2017). "But we found that ectopically expressing miR-29c inhibitors without the treatment of TGF-β1 inhibited the mRNA expression of TTF-1 and E-cadherin, and enhanced the expression of vimentin and α-SMA, which indicated that the inhibition of miR-29c could be sufficient to induce EMT in lung cancer." (PMID 27829234, 2016). "In addition, we observed that Vimentin mRNA, but not Fibronectin mRNA, was decreased in miR-30c-transfected lung cancer cells, A549 and H1299." (PMID 25340791, 2014). "In this study, we found that H1650 lung cancer cells developed resistance to erlotinib and underwent EMT phenotypic changes, which were consistent with decreased expression of the epithelial marker E-cadherin and increased expression of the mesenchymal markers vimentin." (PMID 23520479, 2013). "Furthermore, in Vimentin knockdown cells, neither overexpression nor knockdown of LncPTEN1 changed migration capacity, indicating that Vimentin is indispensable for LncPTEN1-mediated metastasis suppression of lung cancer cells." (PMID 40521243, 2025). "However, we found that PTK7 had no noticeable impact on vimentin levels in lung cancer cells." (PMID 37212485, 2023). "Since NCTD can inhibit the Yap-mediated invasive growth of lung cancer cells, we further checked whether NCTD interferes the YAP-mediated cellular phenotype switching in lung cancer cells by examining the EMT hall marks such as E-cadherin, Vimentin and Fibronectin." (PMID 27903989, 2017). "Moreover, this miRNA was also found able to reduce the GSK3β expression, always in lung cancer stem cells, as well as of activating the Wnt signaling pathway in gastric cancer cells through the induction of epithelial-mesenchymal transition (EMT) and the expression of VIM, SNAI1 and ZEB1." (PMID 27275761, 2016). "Loss of epithelial protein marker E-cadherin, the concurrent upregulation of mesenchymal protein markers vimentin, and the upregulation of MMP-9 play a dominant role in the metastatic process and could be regulated by E2 in various cancers, including breast, ovarian, colon, and lung cancer." (PMID 24222765, 2013). "In this study, mRNA levels of EMT-related genes ECAD, VIM, ZEB1, SLUG was evaluated in Skip N2 metastasis, which is a common entity in the lymphatic spread of the tumor in lung cancer patients and the molecular mechanism has not yet been elucidated." (PMID 35201505, 2022). "VIM, an intermediate filament protein, has been found in exosomes from PC14 (nonmetastatic) and PC14HM (highly metastatic) lung cancer cell lines." (PMID 35158999, 2022). "Exosomes derived from highly metastatic lung cancer cells, PC14HM, express a higher levels of vimentin than those from non-metastatic lung cancer cells, PC14." (PMID 34281588, 2021). "IL-27 has been shown to have non-immune antitumor effects in lung cancer that include suppression of COX-2 and PGE2, reduction of vimentin levels, and inhibition of cell migration and invasion." (PMID 24274066, 2013). "Treatment of lung cancer cells with cycloartocarpin at non-toxic concentrations (0–20 μM) significantly diminished the expression levels of EMT markers, such as vimentin, N-cadherin, and Slug, demonstrating the effect of cycloartocarpin in terms of its inhibition of EMT." (PMID 36500213, 2022). "Treatment of lung cancer cells with artocarpin at non-toxic concentrations significantly reduced the expression levels of EMT markers, such as N-cadherin, Vimentin, and Slug, while increasing E-cadherin, indicating the effect of artocarpin in terms of its inhibition of EMT." (PMID 33920031, 2021).